EBLN3P (endogenous Bornavirus like nucleoprotein 3, pseudogene)
Synonyms: LOC100506710; EBLN3
Gene: Long non-coding RNA gene on chromosome 9 (37,034,202 to 37,090,928, forward strand). Ensembl gene ENSG00000281649.
Diseases named in the same sentence as EBLN3P in open-access papers:
EBLN3P is named in the same sentence as 12 diseases in open-access papers, as found by Europe PMC text mining. Sharing a sentence is not in itself a finding about the gene and the disease. The quoted sentences say what the papers report.
osteosarcoma (12 papers, 2021 to 2025). A usually aggressive malignant bone-forming mesenchymal neoplasm, predominantly affecting adolescents and young adults. "Higher EBLN3P levels have been associated with methotrexate resistance, and downregulation of EBLN3P decreased methotrexate resistance in osteosarcoma cells." (PMID 38843497, 2024). "Moreover, the associations between the expression of EBLN3P and miR-224-5p and the prognosis of osteosarcoma patients were investigated using Kaplan–Meier survival curves and the log-rank test." (PMID 33479458, 2021). "In vitro, functional assays indicated that the knockdown of EBLN3P suppressed osteosarcoma cell proliferation, migration and invasion, demonstrating the potential of EBLN3P as a therapeutic target for osteosarcoma; therefore, we next investigated the underlying mechanism in osteosarcoma cell lines." (PMID 33479458, 2021). "Considerable studies have confirmed that EBLN3P can promote the progression of liver cancer, osteosarcoma and colorectal cancer." (PMID 40019657, 2025). "LncRNA EBLN3P regulated the expression of O-GlcNAc pathway via sponging miR-200a-3p, leading to methotrexate resistance in osteosarcoma cells." (PMID 39019995, 2024). "LNC EBLN3P has emerged as a focal point of interest, given its dysregulation in diverse malignancies such as osteosarcoma, liver cancer, and breast cancer." (PMID 37759607, 2023). "The lncRNA EBLN3P is dysregulated in many cancers, including osteosarcoma, liver, and breast cancers." (PMID 35220878, 2022). "Research reported that endogenous bornavirus-like nucleoprotein 3 pseudogene (EBLN3P) promotes the progression of osteosarcoma." (PMID 36544170, 2022). "Our study shows that EBLN3P can affect the MTX resistance of osteosarcoma cells by regulating miR-200a-3p, an important microRNA that affects EMT." (PMID 36544170, 2022). "In this study, the expression of EBLN3P in osteosarcoma tissue with different methotrexate (MTX) treatment responses was measured." (PMID 36544170, 2022). "The qRT-PCR analysis showed expression of EBLN3P in osteosarcoma was significantly higher than in adjacent tissues." (PMID 36544170, 2022). "Three complementary sequences were designed and synthesized to knock down EBLN3P (EBLN3P-si) in osteosarcoma cells, and the sequence with the highest interfering efficacy was used." (PMID 36544170, 2022). "Our study shows that EBLN3P promotes the metastasis and drug resistance of osteosarcoma through miR-200a-3p/OGT axis." (PMID 36544170, 2022). "Although accumulating evidence has demonstrated the importance of lncRNAs in osteosarcoma, the current knowledge on the functional roles and molecular mechanisms of lncRNA endogenous born avirus-like nucleoprotein (EBLN3P) is limited." (PMID 33479458, 2021). "Although we initially uncovered a novel downstream regulatory mechanism in osteosarcoma cells mediated by EBLN3P in vitro, further research is required to fully elucidate this complex mechanism." (PMID 33479458, 2021). "Accordingly, these data suggested that the regulatory effects of EBLN3P were mediated through the miR-224-5p/Rab10 axis to promote the progression of osteosarcoma cells." (PMID 33479458, 2021). "In conclusion, to the best of our knowledge, the present study is the first to demonstrate that EBLN3P act as a novel oncogene in osteosarcoma." (PMID 33479458, 2021). "The increased expression of EBLN3P and Rab10 and decreased expression of miR-224-5p were observed in osteosarcoma tissues and cell lines." (PMID 33479458, 2021). "Next, 143B cells were transfected with EBLN3P shRNA (si-EBLN3P) and pcDNA3.1-EBLN3P overexpression vector (EBLN3P) to further investigate its possible impact on the aggressive behavior of osteosarcoma cells." (PMID 33479458, 2021). "The present study demonstrated that EBLN3P was markedly upregulated in osteosarcoma tissues and cell lines." (PMID 33479458, 2021).
osteosarcoma (continued). "It was validated that miR-224-5p exerted a reciprocal suppressive effect with EBLN3P expression, and knockdown of miR-224-5p induced the proliferation, migration and invasion of osteosarcoma cells in vitro." (PMID 33479458, 2021). "Further rescue experiments demonstrated that EBLN3P promoted the proliferation and metastasis of osteosarcoma cells via regulation of the miR-224-5p/Rab10 signaling axis." (PMID 33479458, 2021). "The expressions of EBLN3P and miR-224-5p were negatively correlated in osteosarcoma cells and tissues, suggesting the inhibitory effect of EBLN3P on miR-224-5p." (PMID 33479458, 2021). "Recent studies have demonstrated that lncRNAs are crucial regulators of tumor growth and invasion; they have reported that LNC EBLN3P can function as an oncogene in osteosarcoma and lung adenocarcinoma, and the inhibition of EBLN3P can be used in the treatment of cancer." (PMID 36672460, 2023). "Research has demonstrated that EBLN3P is over-expressed in tumors, including osteosarcoma." (PMID 36544170, 2022). "According to the results of previous and ongoing research, it was hypothesized that EBLN3P can affect the malignant phenotype of osteosarcoma cells by upregulating the expression of the Rab10 protein." (PMID 33479458, 2021). "Our data revealed that the knockdown of EBLN3P markedly suppressed the proliferation, invasion and migration of osteosarcoma 143B and U2OS cells, which were enhanced by EBLN3P overexpression, as evidenced by CCK-8, Transwell and wound healing assays, respectively." (PMID 33479458, 2021). "At present, the expressions of EBLN3P and miR-224-5p in osteosarcoma tissues were quantified by reverse transcription-quantitative PCR assay, and the expression of Ras-related protein 10 (Rab10) in osteosarcoma tissues was quantified by immunohistochemistry and western-blotting." (PMID 33479458, 2021). "In the present study, it was also observed that the expression of Rab10 was regulated via the EBLN3P/miR-224-5p axis through bioinformatics analyses; however, whether this compensatory mechanism exists in osteosarcoma requires further investigation." (PMID 33479458, 2021). "Moreover, the influence of the EBLN3P overexpression or knockdown on osteosarcoma 143B and U2OS cells were also explored." (PMID 33479458, 2021). "Herein, whether miR-224 takes part in mediating the functions of lncRNA EBLN3P in osteosarcoma cells has aroused our strong research interest." (PMID 33479458, 2021). "Besides, the overexpression of EBLN3P or knockdown of miR-224-5p were revealed to promote the proliferation, migration and invasion of osteosarcoma cells." (PMID 33479458, 2021). "Dai and colleagues noted that EBLN3P is expressed in osteosarcoma tissues and cell lines." (PMID 34136413, 2021). "The aim was to determine whether EBLN3P can affect the malignant phenotype of osteosarcoma cells by regulating Rab10 protein expression." (PMID 33479458, 2021). "Furthermore, EBLN3P act as a ceRNA to regulate Rab10 expression via competitively sponging to miR-224-5p, thereby regulating the progression of osteosarcoma." (PMID 33479458, 2021). "In addition, EBLN3P could regulate the expression of Rab10 through competitive sponging action with miR-224-5p in osteosarcoma." (PMID 35473552, 2022). "Moreover, knockdown of EBLN3P increased miR-200a-3p expression in MTX-resistant osteosarcoma cells." (PMID 36544170, 2022). "Furthermore, the mechanistic investigations revealed activation of the miR-224-5p/Rab10 regulatory loop by knockdown of miR‐372-3p or overexpression of Rab10, thereby confirming the in vitro role of EBLN3P in promoting osteosarcoma cell proliferation, migration and invasion." (PMID 33479458, 2021). "Some studies have demonstrated that EBLN3P promotes the progression of liver cancer via alteration of microRNA-144-3p/DOCK4 pathway, and osteosarcoma through modifying the miR-224-5p/Rab10 signaling axis." (PMID 35517503, 2022).
osteosarcoma (continued). "We selected 2 osteosarcoma cell lines, MNNG/HOS and MG63 with relatively lower EBLN3P expressions used for further MTX-resistant cell establishment, and finally, the MTX-resistant cell line was successfully established, and IC50 increased from 0.2 to 1 μM for MNNG/HOS, and 0.35 to 1.3 μM for MG63." (PMID 36544170, 2022). "As expected, the RNA expression of EBLN3P was higher and that of miR-224-5p was lower in osteosarcoma tissues compared with non-neoplastic bone tissues (normalized to GAPDH)." (PMID 33479458, 2021). "In addition, the expression levels of EBLN3P, miR-224-5p and Rab10 were accessed in osteosarcoma tissues and non-neoplastic bone tissues." (PMID 33479458, 2021). "In addition, osteosarcoma patients with positive EBLN3P or Rab10 expression had a shorter overall survival compared with that of patients with negative EBLN3P or Rab10 expression." (PMID 33479458, 2021).
liver cancer (10 papers, 2021 to 2025). An epithelial or non-epithelial malignant neoplasm that arises from the liver. "Then, they performed functional assays, which revealed that forced EBLN3P expression resulted in the promotion of the proliferation and metastasis of liver cancer cells via alteration of miRNA-144-3p/DOCK4 signal." (PMID 34109193, 2021). "Our findings were consistent with the oncogenic roles of EBLN3P in liver cancer." (PMID 34109193, 2021). "The lncRNA EBLN3P, functioning as a competitive sponge of miRNA‐144‐3p, positively modulates DOCK4 in the ceRNA pathway and facilitates adverse processes in liver cancer." (PMID 34890108, 2022). "For example, EBLN3P regulates DOCK4 expression via sponging miR-144-3p competitively, thereby participating in liver cancer's progression." (PMID 36371574, 2022). "It has recently been demonstrated that EBLN3P may act as a ceRNA, regulating the expression of DOCK4 through miR-144-3p sequestration, promoting liver cancer cell proliferation, migration, and invasion." (PMID 34827671, 2021).
lung adenocarcinoma (4 papers, 2022 to 2023). A carcinoma that arises from the lung and is characterized by the presence of malignant glandular epithelial cells. "Although we identified a new downstream regulatory mechanism mediated by EBLN3P in lung adenocarcinoma cells, further studies are needed to clarify its underlying mechanisms." (PMID 35473552, 2022). "This study is the first to prove the roles and underlying mechanisms of EBLN3P in lung adenocarcinoma." (PMID 35473552, 2022). "In conclusion, this study demonstrated that EBLN3P silencing inhibits bioactivity and induces apoptosis via the miR-655-3p/Bcl-2 axis, providing a potential therapeutic target for lung adenocarcinoma." (PMID 35473552, 2022). "We found that EBLN3P regulates the proliferation of lung adenocarcinoma cells through the miR-655-3p/Bcl2 axis." (PMID 35473552, 2022). "First, we performed qRT-PCR to examine the levels of EBLN3P and miR-655-3p in the lung adenocarcinoma cell lines A549 and NCI-H23, as well as in BEAS2B cells." (PMID 35473552, 2022). "Silencing the expression of the lncRNA EBLN3P inhibits lung adenocarcinoma cell proliferation and promotes apoptosis by regulating the miR-655-3p/Bcl-2 signaling axis." (PMID 35473552, 2022). "Next, we aimed to confirm whether miR-655-3p is involved in the function of EBLN3P in lung adenocarcinoma." (PMID 35473552, 2022). "In this study, we identified EBLN3P as a novel lung adenocarcinoma-related biomarker." (PMID 35473552, 2022). "An analysis of the co-expression results indicated a positive correlation between LNC EBLN3P and TNPO1 in both lung adenocarcinoma and lung squamous carcinoma." (PMID 36672460, 2023). "Therefore, silencing EBLN3P could be a potential therapeutic strategy for lung adenocarcinoma." (PMID 35473552, 2022).
lung carcinoma (3 papers, 2023 to 2024). "After X-ray irradiation, the knockdown of LNC EBLN3P significantly decreased the protein expression of TNPO1 in lung cancer tissues compared with the control." (PMID 36672460, 2023). "Through RNA sequencing (RNA-Seq), we identified LNC EBLN3P as a regulator of lung cancer cell proliferation and radiosensitivity." (PMID 37759607, 2023). "The basal expression level of LNC EBLN3P was higher in lung cancer cells compared with BEAS-2B cells." (PMID 36672460, 2023). "In this study, we identified LNC EBLN3P as a regulator of lung cancer cell proliferation and radiosensitivity." (PMID 37759607, 2023). "EBLN3P expression is higher in lung cancer tissues and is reduced by carbon ion irradiation." (PMID 38843497, 2024). "According to bioinformatics predictions, down-regulated LNC EBLN3P may play an essential role in the carbon ion radiation-induced suppression of lung cancer by modulating the oncogene TNPO1, which is mediated by miR-144-3p." (PMID 36672460, 2023). "To determine whether LNC EBLN3P is expressed differently in lung cancer cells and normal lung cells, we performed qRT-PCR experiments using normal BEAS-2B cells and four NSCLC cell lines (A549, H1299, HCC827, and Calu-1) for validation." (PMID 36672460, 2023). "Furthermore, the results of BAX expression experiments and hematoxylin–eosin staining showed that knockdown of LNC EBLN3P induced necrosis and apoptosis in lung cancer tissues." (PMID 36672460, 2023). "Down-regulation of LNC EBLN3P expression caused the upregulation of miR-144-3p expression, which in turn caused the level of TNPO1 to increase, thereby inhibiting the viability and enhancing the radiosensitivity of lung cancer cells." (PMID 36672460, 2023). "Furthermore, in a previous study by our team, the expression of LNC EBLN3P in lung cancer cell lines was much higher than in the normal lung bronchial epithelial cell line BEAS-2B, indicating its potential as a therapeutic target in NSCLC." (PMID 37759607, 2023). "In summary, the lncRNA EBLN3P functions as a ceRNA to mediate lung cancer inhibition induced by carbon ion irradiation by sponging miR-144-3p to regulate TNPO1 expression, indicating that EBLN3P may be a promising target for increasing the treatment efficacy of conventional radiotherapy for NSCLC." (PMID 36672460, 2023). "In this study, we found that LNC EBLN3P expression in A549 cells was downregulated by carbon ion irradiation, which was less significantly down-regulated by X-ray irradiation, indicating EBLN3P may play an important role in carbon ion-induced lung cancer cell death." (PMID 36672460, 2023).
breast carcinoma (2 papers, 2022 to 2023). "In breast cancer, the expression of lncRNA EBLN3P was downregulated, and its expression was related to better prognosis of OS and longer progression-free interval (PFI)." (PMID 35220878, 2022).
non-small cell lung carcinoma (2 papers, 2023 to 2024). A group of at least three distinct histological types of lung cancer, including non-small cell squamous cell carcinoma, adenocarcinoma, and large cell carcinoma. "In non-small cell lung cancer cells, EBLN3P can enhance ROS production, which plays a crucial role in regulating radioresistance." (PMID 38843497, 2024).
hepatocellular carcinoma (1 paper, 2022). A malignant tumor that arises from hepatocytes. "Similarly, EBLN3P influenced the progression of hepatocellular carcinoma (HCC) by regulating the expression of DOCK4 via miR-144-3p." (PMID 35473552, 2022).
melanoma (1 paper, 2023). A malignant, usually aggressive tumor composed of atypical, neoplastic melanocytes. "The following seven NRLs were pinpointed as having a vital prognostic influence on melanoma patients through LASSO regression: EBLN3P, AC093010.2, LINC01871, IRF2-DT, AL162457.2, AC242842.1, and HLA-DQB1-AS1." (PMID 37580654, 2023).
tumor (9 papers, 2021 to 2025). "Recent studies have revealed that lncRNAs are new diagnostic and prognostic biomarkers for various tumors including LUAD, and a high expression of the lncRNA EBLN3P is associated with tumor progression." (PMID 35473552, 2022). "We observed that high EBLN3P expression was associated with tumor size (p = 0.032), histology/differentiation (p = 0.013), TNM stage (p = 0.010), and distant metastasis (p = 0.029)." (PMID 34109193, 2021). "Clinical assays revealed that high EBLN3P expression was associated with tumor size, Histology/differentiation, TNM stage and poor prognosis." (PMID 34109193, 2021). "We discovered that LNC EBLN3P knockdown enhanced the increase in ROS levels in tumor cells and the structural damage and functional inhibition caused by 4 Gy X-ray irradiation." (PMID 37759607, 2023). "We examined the related indicators of ROS levels in tumor cells and mitochondrial damage in order to investigate the causes of the increased radiosensitivity of tumor cells after LNC EBLN3P knockdown." (PMID 37759607, 2023). "As expected, xenograft nude mice transfected with si-EBLN3P displayed reduced tumor growth and weight, metastatic nodes in lung tissues, and positive expression of Ki-67, along with downregulated EBLN3P and ANXA3." (PMID 37598115, 2023). "As an important lncRNA, LNC EBLN3P is upregulated and promotes tumor progression in a variety of tumors." (PMID 37759607, 2023). "Through bioinformatics analyses and mechanistic studies, we identified LNC EBLN3P as a potential molecule functioning in the response of tumor cells to heavy ions through a ceRNA regulatory network." (PMID 36672460, 2023). "Clinical assays have demonstrated that high EBLN3P expression is positively correlated with tumor size, differentiation, and TNM stage, indicating a poor prognosis." (PMID 37921852, 2023). "Compared with the X-ray irradiation group, X-ray irradiation combined with LNC EBLN3P knockdown significantly suppressed tumor development." (PMID 36672460, 2023). "A recent study showed that EBLN3P promotes tumor development via targeting miR-323a-3p/UHMK1 in CRC." (PMID 35501324, 2022). "According to the results, EBLN3P expression was distinctly increased in CRC specimens compared with matched non-tumor tissues." (PMID 34109193, 2021). "On the other hand, we also performed in vivo assays to explore the influence of EBLN3P knockdown on tumor growth." (PMID 34109193, 2021). "EBLN3P is an oncogenic lncRNA facilitating CRC tumor formation through the way of being one ceRNA regulating UHMK1's expressing state via sponging miR-323a-3p." (PMID 34109193, 2021). "However, overexpressing ANXA3 while silencing EBLN3P increased the tumor growth rate and weight in nude mice, the number of pulmonary metastatic nodules, and Ki-67 positive expression levels." (PMID 37598115, 2023). "Therefore, the downregulation of LNC EBLN3P plays a radiosensitizing role by increasing the radiation-induced mitochondrial oxidative stress damage in tumor cells." (PMID 37759607, 2023). "However, to our best knowledge, the expression and function of EBLN3P in other tumor types remained largely unclear." (PMID 34109193, 2021). "Mechanistically, VIRMA upregulated LncRNA EBLN3P expression in an m6A-dependent manner, and EBLN3P competed with miR-153-3p to increase VIRMA expression, thereby reducing ferroptosis in tumor cells and enhancing their radioresistance." (PMID 40723784, 2025). "Relative to the si-NC group, the si-EBLN3P group had diminished expression levels of EBLN3P and ANXA3 in nude mouse tumor tissues, decelerated tumor growing speed, reduced tumor weight, and reduced metastatic nodes in lung tissues." (PMID 37598115, 2023). "Through mechanistic experiments, we demonstrated that LNC EBLN3P/miR-144-3p/TNPO1 forms a ceRNA network and plays a crucial role in carbon ion-induced tumor growth inhibition." (PMID 36672460, 2023).